ERBB2 (erb-b2 receptor tyrosine kinase 2)
Diseases named in the same sentence as ERBB2 in open-access papers (continued):
Sharing a sentence is not in itself a finding about the gene and the disease.
gallbladder cancer (79 papers, 2008 to 2026). "A novel transcript, designated ERBB2 i14e, was identified for encoding a novel functional protein, and its protein expression was elevated in gallbladder cancer and strongly associated with worse prognosis." (PMID 39948369, 2025). "Preclinical studies have revealed that genomic ERBB2/ERBB3 mutations promote PD-L1–mediated immune escape in gallbladder cancer through inhibiting the ability of tumor-reactive T cells and attenuating the release of Interferon (IFN-γ) and Interleukin-2 (IL-2)." (PMID 37681031, 2023). "ErbB2 mutations and amplifications are found in 10 to 15% of gallbladder cancers, in 5% of eCCA and less frequently in iCCA (1%)." (PMID 37760415, 2023). "For gallbladder cancer, ERBB2 and BRCA2 mutations were significantly more frequent in our cohort, while ATM mutation was enriched in the cBioPortal cohort." (PMID 32373528, 2020). "Here, we report novel somatic mutations of ERBB2 in gallbladder cancer, and its therapeutic implication in the presence and absence of KRAS (G12 V) and (G13D) mutations." (PMID 30304546, 2019). "The presence of ERBB2 mutations also contrasts with the GAs reported in gallbladder cancer, wherein ERBB2 amplifications have been reported." (PMID 25536104, 2014). "Preclinical study has shown that ERBB2/ERBB3 mutations could promote PD-L1–mediated immune escape in gallbladder cancer." (PMID 37681031, 2023). "Mutations in the ERBB2-gene are among the most common genetic alterations in gallbladder cancer." (PMID 31795490, 2019). "Thus, ERBB2 (V777L) mutations were mutated with an overall frequency of 13% in 6 of 44 gallbladder cancer patients." (PMID 30304546, 2019). "To determine the significance of EGFR and ERBB2 constitutive phosphorylation and KRAS mutant alleles in gallbladder cancer cells, we set out to establish whether expression of ERBB2 is required for gallbladder tumor cell survival." (PMID 30304546, 2019). "Distal cholangiocarcinoma (dCCA), arising from the extrahepatic bile duct (ductus choledochus), and gallbladder carcinoma show overlapping molecular features, including KRAS mutations, ERBB2 amplification, BRCA1/2 alterations, and MSI-H in a minority of cases." (PMID 41535645, 2026). "Studies utilizing animal models, particularly transgenic mice, have illustrated that overexpression of erbB2 in the basal layer of the biliary tract epithelium leads to the development of gallbladder cancer in all mice (100%)." (PMID 38786750, 2024). "Roughly 13% of gallbladder cancers, 18% of extrahepatic cholangiocarcinoma, and 5% of intrahepatic cholangiocarcinoma overexpress HER-2 via ERBB2 or ERBB3 mutations." (PMID 38203714, 2023). "First, the findings of this study clearly demonstrated that KIF11 promotes cell proliferation of gallbladder cancer cell through ERBB2/PI3K/AKT signaling pathway." (PMID 33613109, 2021). "The results of our study also support the view that the ERBB2/PI3K/AKT pathway is one of major signaling pathways in gallbladder cancer." (PMID 33613109, 2021). "In gallbladder cancer progression, researchers also showed that a circRNA generated from the oncogene ERBB2, named as circERBB2 promotes gallbladder cancer progression by regulating PA2G4-dependent rDNA transcription." (PMID 34489401, 2021). "EGFR family genes including EGFR, ERBB2 (HER2), ERBB3 (HER3) were the most activating gene in gallbladder cancer while EPHA2 mutation was found frequently in intrahepatic CCA (iCCA)." (PMID 32093644, 2020). "Consistent with whole exome findings, we observed varying levels of EGFR and ERBB2 constitutive phosphorylation in all gallbladder cancer cell lines based on their phospho‐proteome and follow up validation by western blot analysis." (PMID 30304546, 2019). "Consistent with this, treatment with ERBB2‐specific, EGFR‐specific shRNA or with a covalent EGFR family inhibitor Afatinib inhibits tumor‐associated characteristics of the gallbladder cancer cells." (PMID 30304546, 2019).
gallbladder cancer (continued). "In a modelfor experimental cancer development with a high proportion of ErbB-2(HER2), thetransgenic rats that were used developed gallbladder carcinoma, which suggests thatErbB-2 has a signaling role in gallbladder carcinogenesis." (PMID 25004291, 2014). "Furthermore, testing the effect of GW-2974 on gallbladder carcinoma in BK5.erbB2 mice revealed that targeting Egfr alone or in combination with Erbb2 was effective in preventing and treating gallbladder carcinoma in BK5.erbB2 transgenic mice." (PMID 36476719, 2022). "Circular form of ERBB2 promotes the malignant process in gallbladder cancer." (PMID 31911754, 2020). "ERBB2/HER2 amplification and/or overexpression are particularly enriched in extrahepatic CCA (eCCA) and gallbladder carcinoma, where reported rates range roughly between 10% and 27%." (PMID 41535645, 2026). "In contrast, pCCA and dCCA, as well as gallbladder carcinoma, more commonly exhibit KRAS-alterations and ERBB2-/HER2 amplification/overexpression." (PMID 41535645, 2026). "HER2 overexpression: In 15–20% of extrahepatic CCA and gallbladder carcinomas, there is observed overexpression or amplification of the EGFR family receptor tyrosine-protein kinase erbB-2 (HER2)." (PMID 39065760, 2024). "Next, we examined the expression levels of gallbladder cancer-related markers (ERBB2, CA19-9, CEA, EGFR, Ki67, PD-L1) using immunohistochemistry; all markers were detected in the PDX, PDO, and PT samples with the exception of PD-L1, which is a negative prognosticator for gallbladder cancer." (PMID 36591461, 2022).
cholangiocarcinoma (78 papers, 2008 to 2026). A carcinoma that arises from the intrahepatic biliary tree (intrahepatic cholangiocarcinoma) or from the junction, or adjacent to the junction, of the right and left hepatic ducts (hilar cholangiocarcinoma). "Increased expression of EGFR and related receptors has been noted in O. viverrini-associated CCA, despite the fact that cholangiocarcinoma is characterized by the weak expression of HER2 and ERbB2." (PMID 40732668, 2025). "One of these nine patients had cholangiocarcinoma that harbored ERBB2 missense mutation (V777L), which was the therapeutic target for patients with different types of tumors as reported." (PMID 33635883, 2021). "For example, exosomal cholangiocarcinoma (CCA)-associated circular RNA 1 (circ-CCAC1) derived from ERBB2 gene was discovered to sponge miR-514a-5p to upregulate Yin Yang 1 (YY1), inducing CCA angiogenesis, and regulate CCA tumorigenesis and metastasis." (PMID 38177102, 2024). "Genetic alterations detected in cholangiocarcinomas include fusions and mutations in FGFR2, mutations in IDH1 and KRAS, the BRAF V600E mutation, and ERBB2 amplification." (PMID 37108676, 2023). "Anti‐HER2 targeted therapy in patients with ERBB2 amplification have shown effectiveness in cholangiocarcinoma." (PMID 37814942, 2023). "In cholangiocarcinoma, ERBB2 is a key mediator of bile duct carcinogenesis, and ERBB2 overexpression and hyperactivation are present throughout tumorigenesis." (PMID 34413880, 2021). "EGFR and ErbB2 (HER2) are receptor tyrosine kinases that have been identified on comprehensive genomic profiles to be over expressed in cholangiocarcinoma." (PMID 36345439, 2020). "Here, we demonstrate evidence to support the use of a panel of fluorescently labeled peptides specific for EGFR, claudin-1, and ErbB2 to distinguish BilIN, the precursor lesion, and cholangiocarcinoma from normal biliary epithelium." (PMID 36345439, 2020). "A transgenic mutant with constitutive expression of the ErbB2 in the gallbladder epithelium develops GBC with a 100% penetrance and somatic mutation of Pten leads to biliary hyperplasia and intraheaptic cholangiocarcinoma." (PMID 21303542, 2011). "ERBB2 amplification was the most common predictive marker in gastroesophageal adenocarcinoma, and recent targeted therapy approvals and guideline updates had a significant impact for patients with cholangiocarcinoma and actionable findings in IDH1 (11.2%), FGFR2 (8.1%), or BRAF (1.8%)." (PMID 37682776, 2024). "Here, we hypothesized that EGFR, claudin-1, and ErbB2 are over expressed on the cell surface in BilINs, the precursor lesion, and in cholangiocarcinoma, and can serve as targets for multiplexed imaging for future in vivo imaging to distinguish indeterminant biliary strictures." (PMID 36345439, 2020). "Perihilar cholangiocarcinoma (pCCA; Klatskin tumors), originating at the confluence of the right and left hepatic ducts, more frequently harbors KRAS alterations and ERBB2 (HER2) amplification." (PMID 41535645, 2026). "Indeed, precision medicine approaches in cholangiocarcinoma have rapidly expanded in recent years, and pharmacological targeting of FGFR2 fusions, IDH1 neomorphic mutants, and mutations in kinases including BRAF, HER2 (ERBB2) and NTRK have shown clinical promise." (PMID 37605966, 2023). "Indeed, more than 60% of cholangiocarcinoma patients harbour unique gene aberrations including fibroblast growth factor receptor (FGFR) 2 gene translocations, isocitrate dehydrogenase-1 (IDH1) and KRAS proto-oncogene mutations, and receptor tyrosine-protein kinase erbB-2 (ERBB2) amplification." (PMID 33922362, 2021). "In cholangiocarcinoma, there was a significant correlation between FAM83H mRNA and ERBB2 mRNA (Pearson correlation, R = 0.43, p = 0.008)." (PMID 32460791, 2020).
cholangiocarcinoma (continued). "BRAF, erb-b2 receptor tyrosine kinase 2 (ERBB2), fibroblast growth factor receptor 2 (FGFR2), and isocitrate dehydrogenase 1 (IDH1) genes have been reported as therapeutically relevant genomic alterations in cholangiocarcinoma patients." (PMID 37108676, 2023). "Here, we show in a metastatic cholangiocarcinoma with ERBB2 amplification identified on liquid biopsy (circulating tumor DNA (ctDNA) testing), a dramatic response to now over 12 months of dual-anti-HER2 therapy." (PMID 31453370, 2019). "Given that i) cholangiocytes express the ERBB family members EGFR and ERBB2, and ii) previous reports demonstrated LPS-induced EGFR phosphorylation in cholangiocarcinoma, we performed western blots for phospho-EGFR or phospho-ERBB2 from 0–60 minutes post-LPS treatment." (PMID 25915403, 2015).
small cell lung carcinoma (78 papers, 2005 to 2026). Small cell lung cancer (SCLC) is a highly aggressive malignant neoplasm, accounting for 10-15% of lung cancer cases, characterized byrapid growth, and early metastasis. "Tumor cells acquire resistance to these compounds through multiple mechanisms, including a second-site mutation (T790M) in EGFR, amplification of MET or ERBB2, and conversion to a small cell lung cancer phenotype." (PMID 26047463, 2015). "Less common mechanisms of acquired resistance for the first-/second-generation EGFR-TKI include MET amplification, ERBB2 amplification, transformation to small-cell lung cancer, and others." (PMID 40028158, 2025). "In the case of T790M loss, several genetic alterations have been observed, including those related to transformation to small cell lung cancer, MET amplification, ERBB2 amplification/mutation, PIK3CA mutation, KRAS mutations, and oncogenic gene fusion involving RET, FGFR3, and BRAF." (PMID 34831415, 2021). "Alternative EGFR mutations, MET proto-oncogene or erb-b2 receptor tyrosine kinase 2 (ERBB2) amplification or non-pathway-dependent resistance through transformation into small-cell lung cancers were observed less frequently in biopsies from resistant tumors." (PMID 26949746, 2016).
neuroblastoma (74 papers, 2010 to 2025). Neuroblastoma (NB) is the most common solid, extracranial childhood tumor. "ERBB2 was originally discovered in rat neuroblastoma, and point mutations in the transmembrane region can confer oncogenic activity." (PMID 37340393, 2023). "Additionally, a mutated form of ErbB2 has been identified in a chemical induced rodent neuroblastoma and the nucleotide sequence able to produce transformation was named Neu." (PMID 28286519, 2017). "The ERBB2 gene was first discovered by Weinberg’s group in the early 1980s in rats through experiments on chemically induced neuroblastomas, where its rat homolog “neu” was isolated from the tumour." (PMID 40572608, 2025). "Trastuzumab combined with chemotherapy was given to one patient with neuroblastoma with ERBB2 amplification." (PMID 35681754, 2022). "(Although the designation Neu was originally used to describe an oncogene from nitrosoethylurea-induced rat neuroblastomas, it is nowadays widely used to refer to the human ErbB2/HER2 oncoprotein as well." (PMID 27775011, 2016). "Overall, the kinome-wide RNAi screen identified the PI3K pathway to be involved in HDAC8 inhibitor-mediated anti-neuroblastoma effects and identified additional druggable RTKs, such as ERBB2 and ALK, as targets to sensitize neuroblastoma to HDAC8 inhibitor treatment." (PMID 29515255, 2018). "The first oncogenic receptor tyrosine kinase oncogene, neu, now also known as human epidermal growth factor receptor 2 (HER2) or c-erbB2 was discovered by transinfection and transformation of fragmented DNA from a series of rat neuroblastomas into NIH3T3 cells." (PMID 33923191, 2021). "Given that SORL1, GFRA1/2, ERBB2, are poorly or not expressed in SH-SY5Y neuroblastoma cells according to the Human Protein Atlas (last accessed on 12 September 2023), we made no attempt to model this trophic pathogenesis cascade in vitro." (PMID 37830614, 2023).
brain tumors (72 papers, 2009 to 2025). "We observed lower incidences of KDD in ERBB2, ERBB3 and ERBB4 than EGFR, with distributions mirroring those of other observed oncogenic mutations in brain tumors and NSCLC13–17." (PMID 33654076, 2021). "For example, PPARγ maintains the stemness in ERBB2-positvie breast CSCs, in contrast, PPARγ agonists inhibit the expansion of brain tumor stem cells." (PMID 33482915, 2021). "We showed that CSF ctDNA is more representative of brain tumour genomic alterations than plasma and putative actionable gene mutations and CNA (that is, EGFR, PTEN, ESR1, IDH1, ERBB2, FGFR2) can be identified." (PMID 26554728, 2015). "EGFR/ErbB2 TK inhibitors were well tolerated, but more importantly, showed limited clinical response in brain tumor patients including patients with medulloblastoma (NCT00095940; NCT00077454)." (PMID 26496080, 2015). "The EGFR family member HER-2, also known as ErbB2, is overexpressed in brain tumor cells." (PMID 37190280, 2023). "In addition, IHC analysis of the 13-19 metastatic brain tumor specimen showed strong ERBB2 staining." (PMID 25970776, 2015).
ovarian tumors (69 papers, 1993 to 2025). "The transmembrane glycoprotein, ErbB2/HER2 receptor overexpression has been found to be an important biomarker for a range of different solid human tumors such as mammary and ovarian tumors and has been associated with a poor prognosis." (PMID 35854300, 2022). "ERBB2 protein expression in OV patients was also validated by immunohistochemistry (IHC) stains of ovarian tumors from the Human Pathology Atlas30,31." (PMID 34552204, 2021). "Amplification of the erbB2/neu gene and subsequent overexpression of p185erbB2/neu was identified in 25%–30% of primary breast and ovarian tumors." (PMID 24288089, 2012). "SKOV3ip1 ovarian tumor xenografts abundantly express erbB2, which was confirmed by erbB2 staining of tumor xenografts." (PMID 20500878, 2010). "The SKOV3ip1 ovarian tumor cell line expresses high levels of erbB2, and was, therefore, used to test MSC-AR binding." (PMID 20500878, 2010). "We have also confirmed increased numbers of erbB2-targeted MSCs in ovarian tumors, compared to unmodified MSC." (PMID 20500878, 2010). "We also confirmed an increased concentration of MSC-AR, compared to MSC, in erbB2 positive ovarian tumors." (PMID 20500878, 2010). "The two growth-inhibitory antibodies were also effective in the treatment of tumours established from SKOV3 cells, a human ovarian tumour cell line with high levels of the erbB-2 protein." (PMID 7903153, 1993). "Mucinous tumors are driven by KRAS or ERBB2 amplification, representing about 3% of ovarian tumors." (PMID 38352443, 2024). "To address the relevance of these findings in human ovarian CCC, we evaluated whether ERBB2 amplification is more prevalent in solid peritoneal metastases than primary ovarian tumors in a large cohort of unmatched CCC tumors." (PMID 33199705, 2020). "The ErbB2/HER2 receptor, which is frequently over-expressed in mammary and ovarian tumors, presents an unfavorable prognosis for these cancers." (PMID 35854300, 2022). "In contrast, overexpression/amplification of certain oncogenes like C-MYC, RAS, AKT, EGFR (ErbB1 or HER1), HER2/neu (ErbB2), CSF1 C-MYC, etc., is also well known in ovarian tumors." (PMID 20034397, 2009). "SPAG5 mRNA expression was lowest in wild-type (BRAF/KRAS/ERBB2) ovarian tumors, which differed from nonmutant tumors (P < 0.001) and wild-type (BRAF/KRAS) tumors (P < 0.001)." (PMID 31985007, 2020). "Receptor EGFR, ERBB2, MET, and AXL were strongly co-activated in most primary ovarian tumors." (PMID 21962244, 2011).
head and neck cancer (67 papers, 2003 to 2025). A primary or metastatic malignant neoplasm affecting the head and neck. "We recently reported a similar downregulation of EGFR and ErbB2 levels in Bor-treated head and neck carcinoma cells." (PMID 37069690, 2023). "These associations were additionally supported in CRISPR k.o. of the EGFR or ERBB2 genes in skin, liver, and head-and-neck cancer." (PMID 35614096, 2022). "Notably, however, head and neck cancer (HNSC) has a dearth of unique CAR targets, with only two targets currently in clinical trials, EGFR and ERBB2, suggesting that there may be a critical unmet need to identify additional cell surface targets for HNSC." (PMID 37835579, 2023). "Besides ERBB2, ephrinB1 interacts with ERBB1 that is overexpressed in head and neck cancer." (PMID 33322542, 2020).